GIT2 (GIT ArfGAP 2)
Description:
GTPase-activating protein for ADP ribosylation factor family members, including ARF1.
Synonyms: CAT-2; CAT2; KIAA0148; PKL
Tractability: PROTAC: ubiquitination databases record sites on it; its protein half-life has been measured.
Gene: Protein-coding gene on chromosome 12 (109,929,792 to 109,996,389, reverse strand). Ensembl gene ENSG00000139436.
Subcellular location (Human Protein Atlas): Microtubules
Pathways (Reactome):
Signal Transduction: CDC42 GTPase cycle; RAC1 GTPase cycle; RAC2 GTPase cycle; RAC3 GTPase cycle; RHOJ GTPase cycle; RHOQ GTPase cycle; RHOU GTPase cycle; RHOV GTPase cycle
Gene Ontology:
Molecular function: protein binding; GTPase activator activity; small GTPase binding
Biological process: brain development; regulation of ARF protein signal transduction; regulation of G protein-coupled receptor signaling pathway; synaptic vesicle recycling
Cellular component: focal adhesion; nucleoplasm; synapse; presynapse
Genetic constraint (gnomAD): Loss-of-function variants: 11 observed, 25.98 expected, observed/expected ratio (o/e) 0.42, 90% interval 0.27 to 0.7. The upper end of that interval is the gene's LOEUF score, 0.7, which puts it in group 2 of 6, group 1 being the genes least tolerant of losing a copy. Missense variants: 245 observed, 325.41 expected, observed/expected ratio (o/e) 0.75, 90% interval 0.68 to 0.84. Synonymous variants: 113 observed, 125.26 expected, observed/expected ratio (o/e) 0.9, 90% interval 0.77 to 1.05.
Homologues: Orthologues: chimpanzee GIT2 (97% identical), dog GIT2 (97% identical), pig GIT2 (96% identical), macaque GIT2 (95% identical), rabbit GIT2 (95% identical), guinea pig GIT2 (95% identical), mouse Git2 (93% identical), rat Git2 (92% identical), tropical clawed frog git2 (87% identical), zebrafish git2a (72% identical), zebrafish git2b (71% identical). Paralogues in human: GIT1 (67% identical), APPL1 (17% identical), ARAP2 (16% identical), APPL2 (15% identical), ARAP1 (15% identical), ARAP3 (15% identical), ASAP2 (15% identical), ASAP1 (13% identical), ASAP3 (12% identical), ACAP3 (11% identical), AGAP2 (11% identical), AGAP1 (11% identical), and 16 more.
Diseases named in the same sentence as GIT2 in open-access papers:
GIT2 is named in the same sentence as 23 diseases in open-access papers, as found by Europe PMC text mining. Sharing a sentence is not in itself a finding about the gene and the disease. The quoted sentences say what the papers report.
diabetes (4 papers, 2015 to 2023). "To identify the effects of diabetes-related pathology on GIT2 protein–protein complex interactions, we performed selective GIT2 co-immunoprecipitation (co-IP) (with pre-immune sera as a negative control) in WT and db/db pancreatic cell lysates." (PMID 26834700, 2015). "We found that genomic deletion of GIT2 alters hypothalamic transcriptomic signatures related to diabetes and metabolic pathways." (PMID 26834700, 2015). "Elevation in GIT2 expression levels was reported in an animal model for diabetes and obesity." (PMID 33801150, 2021). "Employing the 400 nM concentration of level of GIT2 siRNA to reduce cellular GIT2 levels, we were able to recapitulate selected expression data generated from our microarray analysis, with specific relevance to beta cell function, metabolism, diabetes, and aging." (PMID 26834700, 2015).
lung carcinoma (4 papers, 2016 to 2025). "RUSC2 interacts with the SHD domain of GIT2 and reduces GIT2 degradation, which regulates lung cancer progression through EGFR signaling." (PMID 34642262, 2021). "While overexpression of GIT2 has been described in the literature in breast and lung carcinomas, this fusion with BRAF is novel in tumorigenesis and has not been described in any other type of tumor, hence it is difficult to predict the effect that the deletion will have on the GIT2 gene." (PMID 29141672, 2017). "Similarly, GIT2 depletion in lung cancer cell lines inhibited cell migration." (PMID 40176062, 2025).
Obesity (3 papers, 2021 to 2023). Accumulation of substantial excess body fat. "GIT2 is known to be the main coordinator of aging processes, including obesity, which is one of the phenotypes of AS." (PMID 36012404, 2022).
Anxiety (2 papers, 2015 to 2022). Intense feelings of nervousness, tension, or panic often arise in response to interpersonal stresses. "There is also evidence to suggest that through common activities related to stress responses RXFP3 and GIT2 together may contribute in a coordinated manner to interconnect anxiety behaviors and stress responses such as hyperphagia or binge-eating." (PMID 35457203, 2022).
breast carcinoma (2 papers, 2019 to 2020). "Furthermore, GIT2 stabilizes FAs by reducing Rac1 activity in the breast cancer cell line MDA-MB-231." (PMID 32426352, 2020). "Also, in a gene expression profile analysis of breast cancer patient samples, GIT2 was found downregulated in a group of lymph node-positive breast cancer patients." (PMID 32426352, 2020).
astrocytomas (1 paper, 2025). "In glioblastomas, which overexpress PKCα compared to low-grade astrocytomas, PKC-mediated phosphorylation of centrosomal GIT2 may enhance microtubule nucleation, thereby promoting the invasive properties of malignant cells." (PMID 40176062, 2025).
colitis (1 paper, 2022). Inflammation of the colon. "Git2 is a G protein-coupled receptor kinase-interacting factor involved in regulating thymocyte positive selection, neutrophil direction perception, and cell motility in the immune response and inhibits colitis by negatively regulating Toll-like receptor signaling." (PMID 35496266, 2022).
COVID-19 (1 paper, 2025). A disease caused by infection with severe acute respiratory syndrome coronavirus 2. "By 6 weeks post-inclusion, COVID-19 hypermethylation of genes with the highest fold-change compared to healthy controls included FAM178B, FYN, TMCC1, TMEM212-AS1, and FIG4, while the top five hypomethylated genes were GIT2, PDGFRB, SEMA6D, TNFAIP8, and ETV6." (PMID 41227320, 2025). "The top molecules in the COVID-19 T1 and T2 data set with the greatest alteration in methylation compared to healthy controls included hypomethylated MUC20, VAV3, CCL20, and mir21 and hypermethylated GIT2, IFNGR2, FCER1G, and OLR1." (PMID 41227320, 2025).
glioblastoma (1 paper, 2025). The most malignant astrocytic tumor (WHO grade IV). "The different regulatory roles of GIT1 and GIT2 in microtubule nucleation are highlighted by differential subcellular distribution of their tagged variants in diverse glioblastoma cell lines." (PMID 40176062, 2025). "In this study, we show that the depletion of GIT2 in glioblastoma cells has a more pronounced and opposite effect on centrosomal microtubule nucleation compared to GIT1." (PMID 40176062, 2025). "We propose that GIT2 phosphorylation provides a novel regulatory mechanism for microtubule nucleation in glioblastoma cells, contributing to their invasive properties." (PMID 40176062, 2025). "In contrast, GIT2 depletion had a similarly strong effect in both mast cells and in glioblastoma cells, leading to an increase in microtubule amount." (PMID 40176062, 2025). "Altogether, our results suggest a novel regulatory mechanism of microtubule organization in glioblastoma cells, where the phosphorylation of the S46 in the ArfGAP domain of GIT2 by PKCs promotes microtubule nucleation, supporting the invasive properties of these highly malignant cells." (PMID 40176062, 2025). "Whether GIT1 and GIT2 also exhibit regulatory effects on microtubule nucleation in glioblastoma cells with elevated levels of γ-tubulin, both at the transcript and protein levels, remains unclear." (PMID 40176062, 2025). "While GIT proteins (GIT1 and GIT2) regulate both cell migration and microtubule organization, their corresponding regulatory mechanisms in glioblastoma cells remain largely unknown." (PMID 40176062, 2025). "To determine whether GIT1 and GIT2 exhibit regulatory effects on microtubule nucleation in human glioblastoma cells, characterized by enhanced expression of both γ-tubulin isoforms, we first conducted immunoprecipitation experiments using whole-cell extracts from U-251 MG glioblastoma cells." (PMID 40176062, 2025). "While the depletion of GIT1 and GIT2 has diverse effects on centrosomal microtubule nucleation, the depletion of either GIT1 or GIT2 resulted in the inhibition of glioblastoma cell migration, as demonstrated by a wound healing assay." (PMID 40176062, 2025). "The increase in microtubule nucleation following GIT2 depletion was not confined to U-251 MG cells, as a similar effect was observed in U-87 MG, and U-118 MG glioblastoma cells." (PMID 40176062, 2025).
glioma (1 paper, 2017). A benign or malignant brain and spinal cord tumor that arises from glial cells (astrocytes, oligodendrocytes, ependymal cells). "We are expanding the knowledge of genetic events that activate the MAPK signaling pathway in low-grade gliomas by describing a novel GIT2-BRAF fusion in PA." (PMID 29141672, 2017).
Immunodeficiency (1 paper, 2013). Failure of the immune system to protect the body adequately from infection, due to the absence or insufficiency of some component process or substance. "Analogous to GIT2 function in osteoclast differentiation, previous studies reported that GIT2 regulates the directional chemotaxis of neutrophils and that the loss of GIT2 in vivo leads to immunodeficiency." (PMID 23296124, 2013).
Insulin resistance (1 paper, 2015). Increased resistance towards insulin, that is, diminished effectiveness of insulin in reducing blood glucose levels. "As the age-dependent development of insulin resistance and the deterioration of glucose-focused oxidative phosphorylation efficiency contribute significantly to accelerated aging mechanisms, we sought to investigate the potential role of GIT2 in systemic metabolic regulation." (PMID 26834700, 2015).
Langerhans cell histiocytosis (1 paper, 2023). Langerhans cell histiocytosis (LCH) is a systemic disease associated with the proliferation and accumulation (usually in granulomas) of Langerhans cells in various tissues. "To the best of our knowledge, we reported here the first case of successful disease control using entrectinib treatment in non-Langerhans cell histiocytosis with novel ROS1::GIT2 fusion." (PMID 36416966, 2023). "Here, we report a pediatric case of non-Langerhans cell histiocytosis affecting the CNS and harboring a novel ROS1 fusion (ROS1::GIT2) identified by comprehensive genomic profiling (CGP), representing a previously unrecognized association." (PMID 36416966, 2023).
melanoma (1 paper, 2025). A malignant, usually aggressive tumor composed of atypical, neoplastic melanocytes. "Interestingly, few gene pairs were specific to cell lineage, with the notable exception of GIT1|GIT2 which was a hit in 12 cell lines, but never in a melanoma line." (PMID 40968372, 2025).
migraine (1 paper, 2023). "A larger study of epigenetic changes in SH2D5, NPTX2, COMT, GIT2, ZNF234, and SOCS1 genes is necessary to understand the processes of migraine chronicity and MOH development." (PMID 37298078, 2023). "One study showed that methylation of some CpG sites of COMT, GIT2, ZNF234, and SOCS1 genes could be important for drug addiction and transformation of migraine into MOH, but studies on larger patient cohorts are needed to fully explore this issue." (PMID 37298078, 2023).
pancreatic cancer (1 paper, 2023). "Its impact on downstream target genes like E2F3, EFNA3, GIT2, MNT, ZNF462, HOXA9, and EGR3 underscores its significance in shaping the aggressive phenotype of pancreatic cancer cells." (PMID 38132457, 2023).
tumor (8 papers, 2008 to 2025). "The GIT2 gene was higher expressed in the tumours from deceased patents and may be implicated in the transformation of epithelial cells to cancer cells as well as inducing cell motility and invasion." (PMID 18778486, 2008). "Among those ASEs associated with metastasis, alternative splicing of GIT2 and TUBB3 might play key roles in tumor metastasis in KIRC patients." (PMID 37810965, 2023). "A positive correlation to LH was found for LGR4 that regulates expression of estrogen receptor and MR1 that mediates tumor immune escape, whereas there was a negative correlation between LH and GIT2, implicated in aging and cellular senescence." (PMID 34758873, 2021). "In this manuscript we describe a tumor with a novel fusion of BRAF with GIT2, hypothesized to result in activation of MAPK in a similar fashion as in PAs with the canonical KIAA1459-BRAF fusion." (PMID 29141672, 2017). "The majority of rearrangements were KIAA1549-BRAF rearrangements (n = 47; 85%), with only one tumor each harboring BCAS1, CCDC6, GIT2, or PTPRZ11 as a fusion partner." (PMID 36854806, 2023). "Highly expressed CD24 competitively binds to ADP-ribosylation factor 6(Arf6) with G protein-coupled receptor kinase-interactor 2(GIT2) and stabilizes Arf6-GTP to activate subsequent ERK pathways, thereby significantly promoting tumor metastasis and 5-FU chemoresistance." (PMID 40486886, 2025). "In a tumour setting, mouse Tregs lacking GIT2 were unable to induce tumour development when compared with wild-type Tregs in an adoptive T cell transfer mouse model." (PMID 33573141, 2021). "GIT2-BRAF fusion has not been reported in the literature in any tumor." (PMID 29141672, 2017).
cancer (4 papers, 2008 to 2025). A tumor composed of atypical neoplastic, often pleomorphic cells that invade other tissues. "GIT1 and GIT2 are key regulators of focal adhesion turnover and cell motility in cancer cells." (PMID 40176062, 2025).
intestinal diseases (1 paper, 2022). "Differential alternative splicing (AS) genes, such as Myo9b, Lsp1, and Git2, have major functions in intestinal diseases." (PMID 35496266, 2022).
GIT2 also shares sentences with these, for which no sentence is quoted: pilocytic astrocytoma (2 papers); cardiovascular diseases (1); schizophrenia (1); type II diabetes (1).